TRAF3 (TNF receptor associated factor 3)
Diseases named in the same sentence as TRAF3 in open-access papers (continued):
Sharing a sentence is not in itself a finding about the gene and the disease.
plasma cell neoplasm (1 paper, 2018). A clonal proliferation of immunoglobulin-secreting plasma cells. "Furthermore, most of the DLBCL and plasma cell neoplasms developed by the TRAF3/BCL-2 double-tg mice are composed by expanded transformed clones that have also undergone class switching and SHM." (PMID 30687320, 2018).
primary immunodeficiency diseases (1 paper, 2012). "TRAF3 regulates both innate and adaptive immunity by modulating signaling mediated by various receptors such as Toll-like receptors, TNF receptors, and lymphotoxin-β receptor (LTBR), and deficiency of TRAF3 has also been implicated in primary immunodeficiency diseases." (PMID 22709905, 2012).
pulmonary fibrosis (1 paper, 2024). Chronic progressive interstitial lung disorder characterized by the replacement of the lung tissue by connective tissue, leading to progressive dyspnea, respiratory failure, or right heart failure. "It directly catalyzes the K29-linked ubiquitination of tumor necrosis factor receptor-acting factor 3 (TRAF3), which regulates TRAF3 activity to promote innate immunity with antiviral effects and plays a role in Wnt signaling, cellular autophagy, and pulmonary fibrosis." (PMID 38785984, 2024).
rhabdomyosarcoma (1 paper, 2021). A rare aggressive malignant mesenchymal neoplasm arising from skeletal muscle. "Upregulated miR-628-5p upon EVA71 infection could target the 3’UTR of TRAF3, which further suppressed TRAF3-mediated IFN-β transcription in rhabdomyosarcoma cells(RD)." (PMID 33809362, 2021).
sarcoma (1 paper, 2018). A usually aggressive malignant neoplasm of the soft tissue or bone. "In addition to shared clonal abnormalities, additional aberrancies were detected in the sarcoma tumor cells, including deletion of a subclone of BRAF (G466A), loss of TRAF3 R505 and new clonal mutations in NF1 and TNFAIP3." (PMID 29463311, 2018).
sarcopenia (1 paper, 2026). Progressive decline in muscle mass due to aging which results in decreased functional capacity of muscles. "Genetic deletion of TRAF3 in myocytes or satellite cells induced early-onset sarcopenia and impaired regeneration, independent of non-canonical NF-κB signaling." (PMID 41890838, 2026).
Sleep apnea (1 paper, 2017). An intermittent cessation of airflow at the mouth and nose during sleep is known as sleep apnea. "Suggestive associations of symptoms of sleep apnea were observed with 11 rare variants (located in KANK2, LCN6, TRAF3, PLEK, HIF1A, SLC45A3, ERCC1/CD3EAP, MRGPRE, GRAMD4, TYW5, CST5)." (PMID 29093733, 2017).
steatosis (1 paper, 2016). Increased lipid within the cytoplasm of cells. "Here we show that tumour necrosis factor receptor-associated factor 3 (TRAF3) is upregulated in mouse and human livers with hepatic steatosis." (PMID 26882989, 2016).
thrombosis (1 paper, 2017). "Time to formation of thrombi in a FeCl3-induced thrombosis model was significantly shortened in the TRAF3 knockout mice." (PMID 29215030, 2017).
tumor (93 papers, 2008 to 2026). "In particular, 82% of the patients carrying TRAF3 mutations were classified in the NF-κB+ group, re-affirming the inactivation of this tumour suppressor as a major driver of constitutive ncNF-κB activity in MM38." (PMID 38514625, 2024). "Bone marrow TRAF3 deficiency was found to inhibit tumor growth and lung metastasis in vivo using a B16 melanoma mouse model." (PMID 39403370, 2024). "We identified tumor necrosis factor receptor-associated factor 3 (TRAF3) as a tumor-derived immune suppressive mediator in ITB1 cells." (PMID 37121997, 2023). "Reconstitution of TRAF3 expression in TRAF3-deficient human MM cells induces apoptosis, demonstrating a tumor suppressive role of TRAF3 in B cell malignancies." (PMID 36776285, 2023). "An increasing number of researches have shown that abnormal changes of TRAF3 gene were associated to abnormal cell growth and mutations and then leaded to tumor formation." (PMID 37798663, 2023). "In myeloid cell-specific TRAF3-deficient mice, myeloid-derived suppressor cells (MDSCs) were found to be significantly expanded, inhibiting the anti-tumor immune response mediated by T cells and promoting cell malignant transformation." (PMID 37798663, 2023). "Combination treatment of TRAF3-deficient B cells and B cell tumor lines with c-Myc inhibitors enhanced their sensitivity to Pim inhibition, suggesting a possible therapeutic strategy." (PMID 31501481, 2019). "This could potentially allow TRAF3-deficient B cells to serve as a reservoir for tumor recurrence and resistance to proliferation-targeting chemotherapy, as well as accumulation of additional oncogenic mutations." (PMID 31501481, 2019). "Although TRAF3 levels inversely correlated with Pim2 expression in tumor-derived B cells as well as their primary cell counterparts, low expression of TRAF3 increased susceptibility to Pim inhibition in human malignant B cells, in contrast to resistance to Pim inhibitors in primary B cells." (PMID 31501481, 2019). "Although the functions of TRAF3 in innate and adaptive immunity are well understood, its roles in tumor malignancy are less explored." (PMID 39932808, 2025). "By targeting the TNF receptor–associated factor 3/enoyl-CoA hydratase 1 (TRAF3/ECH1) axis, they revealed an innovative approach to disrupt tumor metabolism while enhancing antitumor immunity." (PMID 40166928, 2025). "In conclusion, our study demonstrated that loss of TRAF3 in GBM induced mitochondrial translocation of ECH1 and oxidation of PUFAs, thereby inhibiting lipid peroxidation, and promoted tumor growth." (PMID 39932808, 2025). "Conversely, Peli1-cKO in Th17 cells mitigated the tumor-promoting effects of Traf3-cKO and improved Th17 cell differentiation." (PMID 40436857, 2025). "Our analysis of the PELI1-TRAF3 axis in Th17 cell-driven anti-tumor immunity revealed that Traf3-cKO in Th17 cells promoted tumor growth, worsened prognosis, and reduced Th17 cell infiltration." (PMID 40436857, 2025). "In the present study, we demonstrate that the loss of TRAF3 in GBM activated ECH1-mediated metabolism of PUFAs, thereby inhibiting lipid peroxidation and promoting tumor growth." (PMID 39932808, 2025). "In contrast, there was a notable reduction in TRAF3 expression in GBM tumor cells relative to those in LGG tumor cells." (PMID 39932808, 2025). "Site mutation analysis revealed that ubiquitination at STAT6 K450 plays a crucial role in TRAF3-mediated STAT6 activation, which promotes increased expression of M2-associated surface markers as well as tumor progression." (PMID 39403370, 2024).
tumor (continued). "Next, we assessed tumorigenicity by subcutaneously injecting tumor cells from the TRAF3-expressing or KO cell lines with PT or C into mice (n = 5 per group." (PMID 39090283, 2024). "To determine the effect of tumor-derived TRAF3 on immune escape, we created two stable ITB1 TRAF3 knockout (KO) lines, designated TRAF3KO1 and TRAF3KO2." (PMID 37121997, 2023). "Through an unbiased targeted genetic screen, we showed that TRAF3 acts as an immunomodulator that promotes immune escape by suppressing the anti-tumor activity of B cells." (PMID 37121997, 2023). "The strong activation of type-I IFN in TRAF3KO1/2 cell lines and the known association of TRAF3 with MHC-I expression and the activation of tumor immunity prompted us to examine the levels of MHC-I expression on the surface of the tumor cells." (PMID 37121997, 2023). "Increasing evidence indicates that TRAF3 is a tumor suppressor not only in B cell malignancies, but also in a variety of cancers derived from macrophages, osteoblasts, and epithelial cells of different tissues." (PMID 36776285, 2023). "TRAF3 has also been shown to be involved in the pathogenesis of other tumor types, including nasopharyngeal, breast, colon and liver cancers." (PMID 37798663, 2023). "We then validated the potential role of TRAF3 as a tumor-immune suppressive mediator by injecting TRAF3KO1 (henceforth referred to as TRAF3KO) and ITB1 cells into NSG and WT mice and monitoring ascites development and the survival of the mice." (PMID 37121997, 2023). "In particular, increasing evidence indicates that TRAF3 is a tumor suppressor in B lymphocytes and that its absence in B cells is frequently associated with the development of B cell neoplasms, including non-Hodgkin lymphoma and multiple myeloma." (PMID 37207205, 2023). "TRAF3 is a tumor-derived immune-suppressive modulator that influences B-cell infiltration and activation, making it a potential target for enhancing anti-tumor B-cell responses in OC." (PMID 37121997, 2023). "One tumor with the D618A CYLD mutation was classified as NF-κB highly active, but this tumor also harbored simultaneous shallow TRAF3 and CYLD deletions." (PMID 35634245, 2022). "Querying only TRAF3 or CYLD defects would be blind to these alternative NF-κB activating strategies leading to imperfect tumor classification." (PMID 35634245, 2022). "EV-mediated miR-361-3p delivery from hypoxic cells promoted tumor growth and suppressed tumor cell apoptosis in recipient cells by interaction with TRAF3 resulting in the activation of the NFκB pathway." (PMID 35966580, 2022). "Together, these findings emphasize the importance of IL-6 and STAT3 in multiple tumor-suppressive functions of TRAF3." (PMID 36291813, 2022). "These regions contained tumor-related genes, such as Muc16, Pik3, and Bcl2 in amplification regions and Hras, Notch1, Apc2, Ccnd1, Batf2, Dapk3, Smarca4, Traf2, Traf3, Cdk3, and Cdh4 in deletion regions." (PMID 36424557, 2022). "Most of these mutations are found in the gene of TRAF3 but mutations negatively affecting expression or function of TRAF2 were also frequently found defining TRAF2 (and TRAF3) in MM as a tumor suppressor." (PMID 36011046, 2022). "Data analysis of clinical characteristics demonstrated that the level of miR‐361‐3p and TRAF3 expression was relative to the size of the tumour." (PMID 33784010, 2021). "TRAF2 and TRAF3 genes of tumor necrosis factor receptor (TNF-R)-associated factor (TRAF) family are involved in diverse cell signaling, and function as both tumor suppressor gene and oncogene." (PMID 34257589, 2021). "Here we measured the intrinsic apoptosis in premalignant Traf3-/- and TRAF3-sufficient splenic B cells prepared from tumor-free, young adult B-Traf3-/- and littermate control (LMC) mice." (PMID 34745083, 2021). "We next wished to examine the relative sensitivity to Pim2 inhibition of human tumor-derived B cell lines with varying levels of TRAF3 protein." (PMID 31501481, 2019).
tumor (continued). "After it was revealed that TRAF3 plays a powerful B cell-specific role in restraint of homeostatic survival, it has become evident that this TRAF3 role renders it an important tumor suppressor for B cell malignancies, particularly MM and BCL9." (PMID 31501481, 2019). "Although most evidence identifies TRAF3 as a tumor suppressor, studies of the T cell-specific TRAF3−/− (T-TRAF3−/−) mouse model suggest an oncogenic role for TRAF3 in T cells." (PMID 30294322, 2018). "Molecular genetic analysis also revealed unique genomic alterations in the transformed tumor cells, including gain of NF1 and loss of TRAF3." (PMID 29463311, 2018). "Knockdown of TRAF3 in A549 ΔATG5 cells also partially rescued growth in vivo, although tumours did eventually regress." (PMID 29146913, 2017). "In subsequent studies in HNSCC, functional analysis of TRAF3 has suggested a tumor suppressive role of the gene when overexpressed, and increased cell proliferation in the context of depleted TRAF3." (PMID 29034103, 2016). "Using transplanted TRAF3−/− mouse B lymphoma models, we also demonstrated that AD 198 has potent anti-tumor activities in whole animals." (PMID 25960828, 2015). "Taken together, the findings obtained from both the B-TRAF3−/− mice and human patients provide conclusive evidence that Traf3 is a tumor suppressor gene in B lymphocytes." (PMID 25960828, 2015). "Recent studies from our laboratory and others have identified TRAF3, a crucial regulator of B cell survival, as a novel tumor suppressor in B lymphocytes." (PMID 25960828, 2015). "We and others recently identified TRAF3, a cytoplasmic adaptor protein, as a novel tumor suppressor in B lymphocytes." (PMID 25960828, 2015). "Using transplanted TRAF3−/− mouse B lymphoma models, we further demonstrated that oridonin exhibits potent anti-tumor activity in whole animals and is able to prolong the survival of the tumor-bearing mice." (PMID 25960828, 2015). "Purified primary MC1286 tumor cells that had a homozygous deletion of TRAF3 were purified, and then co-cultured with primary bone marrow stromal cells for 7 days, with or without inclusion of 2 uM NIK inhibitor AM-0216." (PMID 24980832, 2014). "Recent studies from our laboratory and others have identified TRAF3, a critical determinant of B cell survival, as a tumor suppressor gene in B lymphocytes." (PMID 25200342, 2014). "We next found that AD 198 vastly inhibited c-Myc protein levels as early as 1 hour after treatment in all TRAF3-/- tumor B cell lines examined in this study." (PMID 24131623, 2013). "In the present study, we report that AD 198 exhibited potent in vitro and in vivo anti-tumor activity on TRAF3-/- tumor B cells, while PEP005 displayed contradictory anti- or pro-tumor activities on different cell lines." (PMID 24131623, 2013). "Our findings thus provide new insights into the complexity of the signaling pathways controlled by PEP005 in TRAF3-/- tumor B cells." (PMID 24131623, 2013). "Here we report that AD 198 has potent anti-tumor effects on TRAF3-/- mouse B lymphomas and human MM." (PMID 24131623, 2013). "AD 198 also inhibited the proliferation of TRAF3-/- tumor B cells, as shown by the marked decrease of the population at the S/G2/M phase (2n < DNA content ≤ 4n)." (PMID 24131623, 2013). "In light of these observations, the present study sought to evaluate the therapeutic potential of PKCδ activation in TRAF3-/- tumor B cells using two pharmacological activators of PKCδ, N-Benzyladriamycin-14-valerate (AD 198) and ingenol-3-angelate (PEP005)." (PMID 24131623, 2013). "Surprisingly, neither AD 198 nor PEP005 increased the nuclear levels of PKCδ at 6 hours after treatment in TRAF3-/- tumor B cells." (PMID 24131623, 2013). "In light of these previous findings, we further assessed the effects of AD 198 on the phosphorylation and cleavage of PKCδ in TRAF3-/- tumor B cell lines." (PMID 24131623, 2013).
tumor (continued). "Taken together, our results demonstrate that both AD 198 and oridonin exhibit in vivo anti-tumor activity on TRAF3-/- mouse B lymphomas." (PMID 24131623, 2013). "We found that AD 198 exhibited potent in vitro and in vivo anti-tumor activity on TRAF3-/- tumor B cells, while PEP005 displayed contradictory anti- or pro-tumor activities on different cell lines." (PMID 24131623, 2013). "We found that AD 198 did not induce the phosphorylation of PKCδ from 10 minutes up to 6 hours after treatment in any TRAF3-/- tumor B cell lines examined in this study." (PMID 24131623, 2013). "AD 198 and PEP005 induced differential effects on TRAF3-/- tumor B cells through distinct biochemical mechanisms." (PMID 24131623, 2013). "In keeping with these goals, recent studies from our laboratory and others have identified TRAF3, a critical determinant of B cell survival, as a novel tumor suppressor in a variety of human B cell lineage neoplasms." (PMID 24131623, 2013). "Detailed mechanistic investigation revealed that AD 198 did not affect PKCδ nuclear translocation, but strikingly suppressed c-Myc expression and inhibited the phosphorylation of ERK, p38 and JNK in TRAF3-/- tumor B cells." (PMID 24131623, 2013). "In the present study, we have uncovered a novel, PKCδ-independent mechanism of the anti-tumor effects of AD 198 that strikingly targets c-Myc in TRAF3-/- tumor B cells." (PMID 24131623, 2013). "Furthermore, the implications of TRAF3-mediated lipid peroxidation for the tumor microenvironment remain poorly understood." (PMID 40166928, 2025). "Combining TRAF3 restoration with ferroptosis inducers or checkpoint inhibitors may offer synergistic benefits, as oxidative stress sensitizes tumor cells to immune-mediated killing." (PMID 40166928, 2025). "In conclusion, TRAF3 maybe function as tumor suppressor by modulating the caspase-1-dependent pyroptosis signaling pathway." (PMID 37798663, 2023). "Moreover, pUL48, a tegument protein of HCMV, can encode DUB for the deubiquitination of TRAF6, TRAF3, IRAK1, IRF7 and STING, thereby inhibiting type I IFN responses, obtaining tumor precursor function, and promoting tumor formation." (PMID 37600809, 2023). "In summary, using transgenic mouse models and scRNA-seq, TRAF3 was identified as a potential tumor suppressor and targeting the TRAF3-NIK axis may provide a potential therapy for ICC." (PMID 36766817, 2023). "Interestingly, a recent study performed sleeping beauty (SB) transposon-based screening in liver-specific PTEN-KO ICC mouse model and identified Traf3 to be the most significant trunk driver for tumor development." (PMID 36766817, 2023). "Together, our findings reveal an interesting “trans-cell” tumor suppressive function of TRAF3 as demonstrated by the evidence that TRAF3 expressed in myeloid cells can suppress the development or progression of tumors derived from another cell type such as B lymphocytes." (PMID 37207205, 2023). "Thus, as so often the activity of TRAF2 and TRAF3, here as tumor suppressors, require support by cIAP1 and cIAP2." (PMID 36011046, 2022). "miR‐361‐3p was transferred to normoxic CRC cells and targeted TNF receptor‐associated factor 3 (TRAF3), which acts as a tumour inhibitor that blocks the noncanonical NF‐κB signaling pathway, thus promoting cell growth of CRC." (PMID 33784010, 2021). "A key tumor suppressor gene, TRAF3, is located within the deleted region." (PMID 32132867, 2020). "In conclusion, Selene could target the mitochondria of tumor cells via the TLR4/TRAF3/MFN1 pathway, induce tumor cell apoptosis, and inhibit inflammatory cytokine secretion in ascites." (PMID 32802180, 2020).